KRAS (KRas proto-oncogene, GTPase)
Diseases named in the same sentence as KRAS in open-access papers (continued):
Sharing a sentence is not in itself a finding about the gene and the disease.
tumor (continued). "In tumours, constitutive activation of KRAS is achieved through point mutations at codons G12, G13 or Q61, which function to lock KRAS into the active GTP-bound state, and thus confer upon the cancer cells the proliferative and pro-survival effects of KRAS signaling." (PMID 40890297, 2025). "The molecular analysis showed that the tumor had a mutation in KRAS (G12C)." (PMID 40507353, 2025). "Additionally, OR calculation showed that KRAS mutation showed a strong association with cribriform tumour histology, N2 lymph node involvement (pN), venous invasion, and a high number of tumour buds (between 7 and 12)." (PMID 39996841, 2025). "Therefore, the presence and quantification of these mutations, including those in KRAS oncogenes, are essential for accurate tumor diagnosis and understanding their mechanisms of development." (PMID 40595916, 2025). "KRAS gene mutations are key drivers of many cancers, but how these mutations alter cellular processes to promote tumor growth remains unclear." (PMID 40427667, 2025). "Further studies have revealed that FASN inhibitors could accelerate the ROS-and iron-dependent cell death, depletion of lipid droplets, and inhibit de novo lipogenesis, causing FA synthesis-dependent cell death in KRAS-positive tumor cells." (PMID 41184283, 2025). "The aim of this study was to quantify the expression levels of the immune checkpoint molecules TIM-3 and Gal-9 in CRC tissues and adjacent non-tumor tissue, and to investigate their associations with key oncogenic mutations, including KRAS, NRAS, BRAF, PIK3CA, and AKT1, as well as MSI status." (PMID 40724985, 2025). "Additionally, emerging biomarkers such as EGFR exon 20 insertions, ERBB2 mutations, NRG1 fusions, Kirsten rat sarcoma viral oncogene homolog (KRAS) G12C, and tumor mutational burden are increasingly considered." (PMID 41020040, 2025). "Additionally, KRAS mutations are associated with an increased presence of tumor-associated macrophages (TAMs), further contributing to immunosuppression." (PMID 40724985, 2025). "The reduction in glycosylation associated with AMG-510 treatment suggests that inhibiting KRAS not only disrupts tumor growth but also interferes with glycosylation pathways, which may further contribute to its anti-tumor effects." (PMID 40164585, 2025). "A recent study has shown that KRAS CNG is associated with the molecular subtype of the neoplasm: “basal-like” cells, more prone to metastasis, usually demonstrate the KRAS CN value of 3 or even 4, while cells with a “classical” phenotype are characterized by an unaltered CN of this gene." (PMID 41009333, 2025). "In the case of KRAS, there is now clear evidence that alterations in allele frequencies or gene dosage at oncogene loci can have a dramatic impact upon tumorigenesis and tumor-associated phenotypes across tumor types." (PMID 39412982, 2025). "Notably, in metastatic cases with KRAS mutation detected by tumor tissue testing, KRAS detection in LB was associated with worse OS (HR = 2.57, 95%CI = 1.42–4.63, P = 0.002)." (PMID 40247392, 2025). "This blockade disrupts oncogenic signaling and tumor growth in KRAS G12C-mutated malignancies." (PMID 41041285, 2025). "Notably, it has been suggested that combining immunotherapy with allele-specific KRAS inhibitors can improve anti-tumor efficacy in KRAS mutant cancers." (PMID 40429703, 2025). "Finally, loss of LKB1 also affects the tumour microenvironment in KRAS-mutant mouse models by inducing elevated collagen deposition due to increased lysine levels and influencing angiogenesis." (PMID 40429821, 2025).
tumor (continued). "Recent research suggests a link between KRAS mutations and the effectiveness of ICIs, as KRAS-driven tumors may possess unique immunogenic features that influence the tumor microenvironment." (PMID 40558308, 2025). "Evidence connecting the tumor microbial microenvironment with oncogenic KRAS mutations was limited." (PMID 40485603, 2025). "KRAS point mutations are the main biomarkers used for the detection of tumor cfDNA." (PMID 41009333, 2025). "An additional key route by which KRAS mutations remodel the TME is modulating tumor metabolism." (PMID 41184283, 2025). "Additionally, KRAS mutations enhance amino acid metabolism, especially glutamine metabolism, to sustain redox balance within tumor cells." (PMID 40437561, 2025). "Notably, tumor-specific neoantigens encoded by KRAS mutations have been identified as highly immunogenic targets for precision cancer vaccines to enhance antitumor immunity, with encouraging preclinical and clinical outcomes." (PMID 40619414, 2025). "Several studies have indicated the presence of KRAS mutations in circulating tumor DNA, which may serve as potential markers for liquid biopsy-based diagnosis." (PMID 39810420, 2025). "Consistent with previous reports, our results indicate that KRAS amplification and additional copy number alterations in genes may confer greater tumor aggressiveness compared to KRAS mutation alone." (PMID 40427213, 2025). "KRAS mutations also induce alterations in cellular metabolism, favoring glycolysis and glutaminolysis to meet the energetic and biosynthetic demands of rapidly proliferating tumor cells." (PMID 40361439, 2025). "Additionally, the immunomodulatory role of KRAS mutations within the tumor microenvironment is becoming increasingly recognized." (PMID 40303413, 2025). "However, the main reason underlying this tumor’s challenging target involves the dynamic and redundant signaling pathways activated by KRAS mutations." (PMID 40510029, 2025). "Therefore, the treatment strategy for KRAS-mutated NSCLC is an important topic in the field of tumor research." (PMID 40506488, 2025). "In addition, programmed death-ligand 1 (PD-L1) expression by 22C3 immunohistochemistry was 40% positive for tumor cells, and the gene mutation analysis showed positive for Kirsten rat sarcoma viral oncogene homolog (KRAS) non-G12C mutation." (PMID 40161114, 2025). "Statistical comparative analyses associated KRAS mutations with the histopathological pattern (p = 0.018), tumour grade (p = 0.030), depth of invasion (pT) (p < 0.001), lymph node involvement (pN) (p < 0.001), venous vascular invasion (p = 0.048), and tumour buds’ number (p = 0.007)." (PMID 39996841, 2025). "Tumours with KRAS/LKB1 co-mutations expressed lower levels of immune markers, including PD-L1." (PMID 40647497, 2025). "In addition, survival in patients with KRAS-mutated tumours also depends on PD-L1 levels, with favourable results for those with high PD-L1 expression." (PMID 40650126, 2025). "Notably, all four patients who achieved pCR had KRAS wild-type tumors, while the single patient with a residual viable tumor demonstrated a KRAS G13D mutation." (PMID 40647530, 2025). "The result showed that the migration, invasion, adhesion, tumor perimeter, and mesenchymal phenotype were increased in the H292 KRAS mutated cells, and everolimus restored sensibility and improved cytotoxicity of EGFR inhibitors in the KRAS mutant NSCLC cell lines." (PMID 40123978, 2025).
tumor (continued). "KRAS mutations lead to the activation of KRAS protein, which promotes tumor cell proliferation." (PMID 40547026, 2025). "This immune regulation function of KRAS-mutations may improve tumor cell survival in the brain, but it also makes NSCLC BMs with KRAS-mutations more susceptible to treatment with immune checkpoint inhibitors (ICIs)." (PMID 40076927, 2025). "RFS was shorter in KRAS mutated patients without a statistical significance (mRFS 25.84 months vs. 31.99 months; p=0.23) suggesting that the KRAS mutation may have a deleterious effect and that the tumor cells may be inherently resistant to adjuvant therapies." (PMID 41001026, 2025). "dPCR analysis showed that a total of 95.9% and 75.5% of primary tumor samples harbored the KRAS p.G12D mutation, with a median %mutation of 15.2% (IQR 0.2–26.2%) and 16.7% (IQR 10.9–34.5%), when the %mutation cutoff for a positive reaction was set at >0% and >0.1%, respectively." (PMID 40943438, 2025). "In addition, the KRAS mutation dose demonstrated a stronger clinical association than did tumor cellularity." (PMID 39779977, 2025). "Second, it enabled the discovery of novel insights: we identified mutations in genes including KRAS, which may cooperatively contribute to tumor pathogenesis." (PMID 41383551, 2025). "There was a strong correlation between the percentage of KRAS p.G12D mutations determined in tumor DNA samples by the two methods, with a Spearman’s rho of 0.666 (p < 0.001) and 0.670 (p < 0.001) when %mutation of >0% and >0.1% were considered for a positive reaction in dPCR, respectively." (PMID 40943438, 2025). "Similarly, siRNA-loaded BEVs targeting KRAS mutations have shown promising results in reducing tumor growth in pancreatic cancer mouse models, suggesting potential for precision medicine approaches." (PMID 40507254, 2025). "In addition to directly regulating immune checkpoint expression, KRAS-mutated tumor cells have been shown to enhance the secretion of IL-10 and TGF-β1 through activation of the MEK-ERK-AP1 signaling pathway." (PMID 40303413, 2025). "Additionally, as the tumor progresses, one KRAS mutant allele often leads to genomic loss of the remaining KRAS allele." (PMID 40707469, 2025). "As KRAS mutations are more frequent in smokers—who typically have higher tumor mutational burden and neoantigen load—this may further support ICI responsiveness." (PMID 40558308, 2025). "To date, MUC1 has shown great potential as a diagnostic marker and tumor treatment in NSCLC with KRAS mutation but its role in PDAC and CRC is almost unknown." (PMID 40013338, 2025). "Taken together, these observations indicate that FSP1 and GPX4 cooperatively establish a dual-layer antioxidant defense system in PDAC cells, enabling KRAS-mutated tumor cells to bypass the “ferroptosis checkpoint” and facilitating their survival and proliferation." (PMID 40862825, 2025). "Interestingly, IL-22 was closely related to the c-Myc pathway in CRC cell lines with KRASG13D mutation, where it cooperated with KRAS mutations to promote tumor cell proliferation." (PMID 40611261, 2025). "We next examined the uptake of RBCEVs by KRAS-mutated tumor cells in vivo." (PMID 40585984, 2025). "Co‐mutations in KRAS and a high tumor mutation burden (TMB) are frequently observed." (PMID 40622001, 2025). "However, CRC cancer cells with KRASG12D mutations transferred mutated KRAS protein to neutrophils via exosomes, thereby promoting the pro-tumor factor neutrophil extracellular trap (NET) by upregulating IL-8 expression." (PMID 40611261, 2025).
tumor (continued). "These variants leading to BRG1 protein loss co-mutated with KRAS may lead to cancer treatment resistance by creating an immunosuppressive tumor microenvironment and impairing the effectiveness of DNA repair mechanisms." (PMID 41007704, 2025). "Our data support the role of ctDNA in capturing ongoing tumor evolution, suggesting that specific mutations, including rare variants in KRAS, EGFR, and PIK3CA, may contribute to resistance and progression." (PMID 40652269, 2025). "The most commonly mutated oncogene was KRAS, altered in 33% of tumours." (PMID 41015991, 2025). "In this review, we aim to summarize current knowledge on KRAS-related metabolic alterations in cancer cells and explore the prevalence and significance of KRAS mutation in shaping the tumor microenvironment and influencing epigenetic modification via various molecular activities." (PMID 39806421, 2025). "Hence, targeting cells with KRAS mutations by small interfering RNA (siRNA), short hairpin RNA (shRNA), or KRAS mutation-specific small molecule inhibitors can be considered as tumor cell-specific targeting strategy with less off-target side effects." (PMID 38954230, 2024). "This confirms the specific targeting of the KRAS G12V mutation tumor in vivo by HLA-G12V/CD3 BiTE." (PMID 38752985, 2024). "The development of these mutations following anti-EGFR targeted treatment, can be a consequence of alterations rising from pre-existent KRAS altered clones, or due to new mutations derived from stress conditions induced by targeted therapy to the tumor and tumor microenvironment." (PMID 38711991, 2024). "CRC patients could benefit significantly from combined therapies that target not only KRAS but also the cancer-associated fibroblasts (CAFs) within the tumor microenvironment." (PMID 39061234, 2024). "However, mutations in both EGFR and KRAS showed unique allelic differences determined by smoking status that are known to alter tumor response to targeted therapy." (PMID 39052387, 2024). "However, in NSCLC, the effects of KRAS mutations on tumor immunity are multifaceted and often contradictory." (PMID 39113608, 2024). "However, when a tumor has both the KRAS mutation and MSI, the magnitude of up-regulation was the greatest." (PMID 39125664, 2024). "We assessed HLA-G12V/CD3 binding to KRAS G12V mutation tumor." (PMID 38752985, 2024). "Indeed, we and others have previously shown that CIMP+ tumours are associated with specific clinicopathologic features including early stage, location in the proximal colon, poor or mucinous histopathology, and KRAS and BRAFV600E mutations." (PMID 38716804, 2024). "The most common KRAS mutation type in tumor was G12D (51%), followed by G12V (26%)." (PMID 38378604, 2024). "Thus, according to ARMS–HRMA, KRAS mutations in tumor samples were as follows: WT in 20, G12D in 32, G12V in 22, G12D/G12V in 2, G12R in 10, G12C in 1, and G12D/G12C in 1 patient." (PMID 39456638, 2024). "Furthermore, KRAS mutations can vary among different tumor sites or liquid biopsies from the same patient due to tumor heterogeneity." (PMID 38938409, 2024).
tumor (continued). "KRAS mutation status in tumor was marginally significant (p = 0.054)." (PMID 39456638, 2024). "There is a high concordance level in KRAS mutations between ctDNA and primary tumor tissue." (PMID 39156972, 2024). "Notably, RAS-dependent metabolic adaption is likely tumor-specific, owing to the prevalence of specific KRAS mutations." (PMID 38576709, 2024). "In addition, recent studies have shown that tumor burden score is a good marker for prognosis and is associated with some molecular mutations such as KRAS." (PMID 39165688, 2024). "Additionally, KRAS WT cases showed higher microsatellite instability and tumor mutational burden, potentially making them more responsive to immune checkpoint inhibitor therapies." (PMID 38666907, 2024). "Examination of tumor mutations in varying risk categories showed that KRAS mutations were more prevalent in the high-risk subgroup than in the low-risk one.This suggests that the high-risk group is more aggressive and less responsive to treatment, leading to a poorer prognosis." (PMID 38956290, 2024). "Here, we investigate whether there is prognostic value in combining KRAS mutational status with tumor size to aid in clinical stratification of potentially treatment-responsive subgroups in early-stage NSCLC." (PMID 38884086, 2024). "Interestingly, a significant relationship was observed between KRAS mutation status and the type of tumor growth." (PMID 38465160, 2024). "Additionally, because both KRAS c.34G>T (p.G12C) mutation and BRAF mutation were associated with CIMP‐high status, we conducted exploratory analyses comparing clinical and tumor characteristics between KRAS c.34G>T (p.G12C)‐mutated and BRAF‐mutated tumors." (PMID 39039804, 2024). "The mutation of the KRAS gene may promote the proliferation of mucous-producing tumor cells and the secretion of mucin (MUC) by activating the mitogen-activated protein kinase (MAPK) downstream signaling pathway." (PMID 38611084, 2024). "KRAS mutation showed a positive relationship with the type of tumor growth (P=0.035)." (PMID 38465160, 2024). "As KRAS activation by hallmark mutations is an early event that occurs in over 90% of all PDACs but is also frequently mutated in other cancers, it has fundamental importance for understanding the changes that drive tumour formation through secretory factors." (PMID 38678032, 2024). "Glucose deprivation contributes to the development of KRAS pathway mutations in tumor cells." (PMID 39466877, 2024). "The fact that PF139 also harbors KRAS mutation may also raise interesting questions about the association of oncogenic KRAS and HIF1α in tumor progression." (PMID 39227650, 2024). "Several factors influence survival in CRLM, such as the progression-free interval after surgery for the primary tumor, whether the tumor is metachronous or synchronous, KRAS or BRAF mutation status, CEA levels, and extrahepatic disease." (PMID 39562379, 2024). "In addition, other clinicopathological characteristics including age, gender tumor location and stage were determined and their association with KRAS and BRAF V600E mutations described." (PMID 39364024, 2024). "And its efficacy can vary depending on genetic mutations within the tumor, such as KRAS and PIK3CA mutations, which may influence resistance to certain drugs." (PMID 39555098, 2024). "KRAS mutation was associated with higher tumor pathological stage." (PMID 39364024, 2024).